TIMP3 (TIMP metallopeptidase inhibitor 3)
Diseases named in the same sentence as TIMP3 in open-access papers (continued):
Sharing a sentence is not in itself a finding about the gene and the disease.
tumor (continued). "In contrast, TIMP-1 expression displays a tendency to increase in association with higher tumor grades, while TIMP-3 and -4 have a tendency to decrease." (PMID 26431549, 2015). "It has been suggested that EFEMP1 and TIMP-3 form a strong association which regulates matrix composition and affects tumor progression." (PMID 25987128, 2015). "This indicates haploinsufficiency whereby the loss of even one allele of Timp3 is able to confer tumor protection." (PMID 25807548, 2015). "The individual loss of Tnfr1 (PyMT Tnfr1−⁄−) also led to a longer time to tumor palpation, similar to PyMT Timp3−⁄− and PyMT Tnf-/- cohorts." (PMID 25807548, 2015). "In the mammary gland, Timps are highly expressed in the stroma and through the transplantation of tumor cells we observe that Timp3 deficiency in the host is sufficient to delay the growth of early, but not advanced tumor cells." (PMID 25807548, 2015). "Tumor size (P = 0.000), status of nodal involvement (P = 0.000), tumor stage (P = 0.000), and tumoral TIMP-3 expression (P = 0.026) were significantly associated with disease-free survival." (PMID 25510449, 2014). "rs1962223, which is near the promoter region of TIMP3, was associated with a 3-fold increased risk of death for patients who carried the CG genotype after adjustment for patient age, tumor location, disease stage and treatment." (PMID 23527119, 2013). "This is the first immunohistochemical study to show that TIMP-3 protein within cancer cells is associated with tumor phenotype." (PMID 17032447, 2006). "Furthermore, TIMP3 showed substantial and favorable relationships with gene markers linked to tumor-associated macrophages (TAMs) and macrophages." (PMID 41009435, 2025). "Consequently, TIMP3 expression is linked to the tumor microenvironment and immune cell infiltration in response to immunotherapy." (PMID 41009435, 2025). "Considering the dual effects of immunomodulatory factors, chemokines, and their receptors on tumor progression, additional in vitro and in vivo studies are necessary to investigate the underlying mechanism linking TIMP3 to the immune environment and clinical prognosis." (PMID 38410497, 2024). "However, significantly lower tumor T status was found in TIMP-3 SNP rs9862 CT + TT variant than the wild type (OR: 0.515, 95% CI: 0.289-0.917, P = 0.023)." (PMID 36860920, 2023). "However, the TIMP-3 SNP rs9862 CT + TT genotype is associated with lower tumor T status in the UCC patients." (PMID 36860920, 2023). "In addition, a significant association was observed between TIMP3 and age (p = 0.036, Wilcoxon’s test) or tumor stage (p = 0.011, Fisher’s exact test)." (PMID 35701814, 2022). "In addition, further in-depth analysis of the effects of different TIMP3 genetic polymorphisms and their mRNA and protein expression levels on tumor progression, biochemical recurrence, and disease prognosis of prostate cancer is required." (PMID 36612628, 2022). "The tissue inhibitor of metalloproteinase (TIMP)-3, encoded by the TIMP3 gene, may inhibit tumor growth, invasion, and metastasis of several cancer types." (PMID 36499314, 2022). "TIMP-3 is often silenced in malignancies and its deficiency in mouse enhances tumor progression." (PMID 33673623, 2021). "A study indicates that a loss of TIMP3 is associated with tumor invasion in experimental animals." (PMID 33730072, 2021). "Moreover, the TIMP-3 methylation pattern was reversely associated with lung tumor stage of patients, but the TIMP-3 expression was closely related with tumor development." (PMID 29467412, 2018). "Furthermore, promoter methylation of both CDKN2A (p14ARF) and MGMT has been associated with tumour stage and the addition of GSTP1 and TIMP3 promoter methylation allowed to discriminate invasive tumours." (PMID 30149597, 2018).
tumor (continued). "TIMP-3’s effectiveness is likely due to its combined ability to inhibit metalloproteinases (MPs), cause apoptosis and decrease proliferation in VSMCs and a variety of tumour-derived cell lines." (PMID 29617412, 2018). "TIMP3 exerts its anti-proteolytic function either at the invasion front of an infiltrating tumor to quench tumor-associated ECM degrading activity or in the stroma itself, where soluble proteases liberate ECM-tethered factors that assist the cancer cell in migration and invasion." (PMID 24359512, 2013). "The inverse association of TIMP-3 protein with a proliferation marker is in line with its inverse correlation with nuclear grade, because the number of mitoses is coevaluated in the assessment of tumor's nuclear grade." (PMID 17032447, 2006). "This is interesting as we know that loss of TIMP3 expression may enhance the invasive potential of certain tumours." (PMID 15846300, 2005). "Therefore, our analysis suggests that high KDM1A and low TIMP3 expressions may promote tumor metastasis, which is associated with poor NSCLC prognosis." (PMID 27058897, 2016). "Using the TIMER and TISIDB databases, the relationship between TIMP3 expression and tumor-infiltrating immune cells (TIICs) in CRC was examined." (PMID 41009435, 2025). "TIMP3 functions as a tumor suppressor by inhibiting MMPs, promoting apoptosis, and preventing angiogenesis." (PMID 41294900, 2025). "Versican (VCAN) and LAMC1, which are strongly associated with tumor progression and increased metastasis risk, were identified only in CRLM-SD, whereas TIMP3 and decorin, which are linked to an opposing effect in cancer, were found exclusively in CRLM-CA." (PMID 40617497, 2025). "This is consistent with a concept in which TIMP3 suppresses aggressive tumor behavior through ECM control, and its depletion encourages an inflammatory, angiogenic, and pro-invasive milieu." (PMID 41009435, 2025). "Anticipating further research on TIMP3’s biological function in the tumor immune milieu, we envision a clearer understanding of its role in cancer prognosis." (PMID 41009435, 2025). "Tissue inhibitor of metalloproteinases 3 (TIMP3) is the major endogenous inhibitor of matrix metalloproteinases (MMPs) and inhibits tumor growth, invasion, metastasis and angiogenesis." (PMID 40357367, 2025). "This suggests that, for the majority of tumor types, TIMP3 has superior predictive potential for immunotherapy response, as many modules showed AUC values of more than 0.5." (PMID 41009435, 2025). "TIMP3, a member of the tissue inhibitors of metalloproteinases family, is vital for regulating immune infiltration and inhibiting tumor growth in multiple cancer types." (PMID 41009435, 2025). "In vitro and in vivo studies using a variety of tumor types have revealed that high TIMP3 expression induces apoptosis of tumor cells." (PMID 41009435, 2025). "In triple-negative breast cancer (TNBC), TIMP3 functions as a tumor suppressor by strongly inhibiting angiogenesis, metalloprotease activity, and cellular migration." (PMID 40861257, 2025). "This suggests that, when TIMP3 expression increases, so does the proportion of these Tregs, especially in tumor tissue relative to normal or peripheral samples." (PMID 41009435, 2025). "Ultimately, expanding our research regarding TIMP3’s molecular mechanisms in influencing cancer patient prognoses offers potential for improving tumor diagnosis and treatment." (PMID 41009435, 2025).
tumor (continued). "Web-based resources were significantly helpful in exploring the function of TIMP3 in transcriptional alterations, functional networks, and tumor immunity." (PMID 41009435, 2025). "Although TIMP3 has tumour-suppressive potential, some studies have suggested that TIMP3 promotes carcinogenesis." (PMID 38542164, 2024). "In total, 74% of patients had significantly lower TIMP3 expression and this reduction was found to have a noteworthy impact on tumor biology." (PMID 39199614, 2024). "We also noted that ALDH1A3 upregulated TIMP metallopeptidase inhibitor 3 (TIMP3) in MDA‐MB‐231 cells, and TIMP3 was highly co‐expressed with ALDH1A3 in the TCGA Cell 2015 patient tumour dataset." (PMID 37753740, 2024). "TIMP3 expression levels in different tumour stages are downregulated compared to those in the normal tissue group." (PMID 38542164, 2024). "TIMP3 shows higher expression in cells situated between the central and peripheral tumor regions, suggesting its potential role in tumor suppression." (PMID 39764138, 2024). "In the ccRCC microenvironment, tissue inhibitor of TIMP3, secreted mainly by tumor endothelial cells (TEC), is downregulated in tumor tissues of hypertensive ccRCC patients." (PMID 39114567, 2024). "Reduced TIMP3 expression is thought to result from aberrant promoter hypermethylation and miRNA regulation in several tumour types." (PMID 38542164, 2024). "On the other hand, miR-103 targets the expression of TIMP-3 and stimulates tumor growth and invasion." (PMID 39001478, 2024). "TIMP-3 also exhibits antiangiogenic and antitumor effects by downregulating vascular endothelial cadherin expression, highlighting the diverse impacts of TIMP-3 on neovascularization and tumor progression." (PMID 38672182, 2024). "In NSCLC, TIMP3 silencing by EZH2 protein, known to cause histone lysine methylation (H3K27), was linked to tumor progression and metastasis." (PMID 36830984, 2023). "In the TCGA analysis, the TIMP-3 showed higher level of mRNA expression in the UCC with advanced tumor stage, tumor T status and lymph node status." (PMID 36860920, 2023). "Nevertheless, higher expressions of some factors were observed by stromal cancer-associated fibroblasts compared with fibroblasts from previous biopsy (MMP-9 and TIMP-3) or to fibroblasts from non-tumor zones of prostatectomy (MMP-2 and TIMP-3)." (PMID 37108185, 2023). "Comparing the expression of MMPs/TIMP-3 in tissue from biopsies before cancer diagnosis and in the tumor zone of the prostatectomy specimen revealed several significant differences." (PMID 37108185, 2023). "The tissue inhibitor of metalloproteinases 3 (TIMP3) is a tumor-suppressing substance that, if eliminated, will accelerate tumor invasion and metastasis." (PMID 37587156, 2023). "About the TIMP-3 rs9619311 genotype frequencies and the clinical characters of UCC, a similar tumor status was found in each parameter between the TIMP-3 rs9619311 TC + CC variant and TIMP-3 rs9619311 TT wild type (all P > 0.05)." (PMID 36860920, 2023). "Mature miR-17-5p can coordinate with its passenger strand miR-17-3p totarget tissue inhibitor of metallopeptidase 3 (TIMP3), leading toincreased tumor cell proliferation, survival, and invasion, ultimately inducingprostate tumor growth and invasion." (PMID 39076378, 2023). "In the present study, we also evaluated the evolutionary changes in the expression of MMPs/TIMP-3, both in the area where the tumor arose and in those far away from them in the previous benign biopsy and the prostatectomy specimen." (PMID 37108185, 2023). "One TIMP family member, the TIMP3 protein, inhibits tumor growth by preventing the adhesion of cells to ECM and promoting the activation of apoptosis via the caspase-8 pathway." (PMID 36830984, 2023). "About the percentage aspect, 76.6 percent of TIMP-3 SNP rs9862 CT + TT genotype showed advanced tumor T status while 86.4 percent of TIMP-3 SNP rs9862 CC genotype illustrated advanced tumor T status." (PMID 36860920, 2023).
tumor (continued). "After the analyses, a significantly higher TIMP-3 mRNA level was found in high tumor stage (P < 0.0001), high tumor T status (P < 0.0001) and high lymph node status (P = 0.0005)." (PMID 36860920, 2023). "Trehalose significantly increased cell death (P < 0.001 vs. UVB group), exhibiting a clearance effect on tumor cells, and TIMP3 and ATG9A siRNA inhibited trehalose-induced cell death under UVB exposure conditions (P < 0.01 vs. UVB + TRE group)." (PMID 35450405, 2022). "The inhibition was indicated by the upregulation of p27Kip1 and TIMP3, two well-known tumor suppressors." (PMID 36147518, 2022). "Previous reports show that TIMP3 can act as a tumor suppressor and inhibits the progression and invasion of NSCLC cells." (PMID 35480306, 2022). "As TIMP-3 inhibits tumor growth, invasion, and metastasis of several cancer types, it was proposed as a human tumor suppressor." (PMID 36499314, 2022). "The TIMP3 and RECK genes encode for proteins that inhibit matrix metalloproteinase, and have been demonstrated to play a tumor-suppressor role by inhibiting angiogenesis, invasion, and metastasis." (PMID 35625697, 2022). "Once the cells restored the tumor-suppressing function of p27Kip1 and TIMP3, they retained the therapeutic effect of PTX." (PMID 36147518, 2022). "Herein, we found that the loss of TIMP3 induced by the knockdown of circCSNK1G3 notably repressed the EMT process in RCC cells, indicating that circCSNK1G3 can lead to tumour metastasis by promoting the EMT process in RCC." (PMID 33560588, 2022). "The comparison of differentially expressed genes, specifically in FGFRL1-KD xenografts versus controls, revealed high-ranking upregulated genes such as BMP7 and TIMP3, with specific activities related to tumor–stromal interactions and tumor suppression." (PMID 35053442, 2022). "In previous studies, TIMP3 was regarded as a tumor suppressor, since the knockout of TIMP3 can result in tumor aggressiveness and poor prognosis." (PMID 36164322, 2022). "The expression of FBN1, RARRES1, and TIMP3 was positively correlated with multiple tumor-related pathways." (PMID 36424614, 2022). "In single-cell samples, TIMP3 had a significantly high expression in mesenchymal cells, and studies demonstrated that TIMP3 can promote tumor progression through EMT, which also verifies our conclusion." (PMID 36424614, 2022). "TIMP3 expression was also consistently increased in DEN-induced liver tumours compared with non-tumour livers." (PMID 35867177, 2022). "In fact, the authors observed that when miR-181b was inhibited, the EMT-promoting effects caused by increased circ-CSNK1G3 were notably reversed, and overexpression of TIMP3 was also able to reverse tumor growth." (PMID 35813211, 2022). "Conversely, Mmp2 (tumor progression) and Timp3 (inhibitor of metalloproteinases) mRNA expression was significantly repressed after LLC challenge in Igf1rfl/fl mice, while this repression was milder in CreERT2 mice." (PMID 35688943, 2022). "Tissue inhibitors of metalloproteinases (TIMPs) are proverbial inhibitors of metalloproteinases and composed of four structurally related members (TIMP1, TIMP2, TIMP3, and TIMP4), associated with tumor invasion and angiogenesis." (PMID 35559040, 2022). "ALKBH5 inhibits tumor motility and stemness by demethylating TIMP3, LncRNA NEAT1, WIF1, and LncRNA KCNK15-AS1." (PMID 33428593, 2021). "Considered a tumor suppressor, EZH2 plays a role in silencing CDH1, FOXC1, DAB2IP, and TIMP3, events linked to metastatic progression." (PMID 34680307, 2021). "The expression of TIMP-1 and TIMP-2 was detected in stromal cells, and TIMP-3 expression in tumor epithelial cells, in the infiltrative area." (PMID 34204372, 2021). "In a series of 18 matched tumour and healthy donor tissue samples, Wild and colleagues identified TIMP3 promotor methylation in 44% of tissue tumour samples." (PMID 34439335, 2021).
tumor (continued). "Tissue inhibitor of metalloproteinase-3 (TIMP3) is a putative tumour suppressor gene which inhibits metalloproteinase, resulting in reduced cellular growth, cellular migration and invasion." (PMID 34439335, 2021). "miR-191 promotes EMT and HCC tumor growth by directly targeting TIMP3 and inhibiting TIMP3 expression." (PMID 33791228, 2021). "TIMP3 is a tissue inhibitor of metalloproteinase and is able to inhibit tumor angiogenesis, tumor growth, invasion, and metastasis of several malignancies." (PMID 33669363, 2021). "TIMP-3 has been considered as a tumor suppressor in several human cancer types, as it inhibits cancer cell migration and invasion." (PMID 33673623, 2021). "A recent study indicated that miR-221 is upregulated by AP-1 transcription factor and involved in the downregulation of TIMP3 gene during tumor development." (PMID 33730072, 2021). "It inhibits the tumor suppressors TIMP3, PTEN and p21, resulting in tumor development via increased cell cycling, proliferation and tumor metastasis." (PMID 34226620, 2021). "One of the most differentially expressed genes, TIMP3, coding for the tissue inhibitor of metalloproteinase-3, a glycoprotein with tumor-suppressing properties was upregulated by all treatments." (PMID 32244462, 2020). "CircSMARCA5 is downregulated in HCC tissues and inhibits proliferation, invasion, and metastasis of HCC cells by promoting the expression of the tumor-suppressor TIMP3 by sequestering miR-17-3p and miR-181b-5p." (PMID 33195421, 2020). "In tumor tissues, overexpression of TIMP-3 significantly reduces the vascular density of tumors, resulting in a smaller tumor volume." (PMID 32762747, 2020). "Traditionally, as a potential tumor suppressor gene, TIMP-3 specifically suppresses the activity of MMPs, leading to the inhibition of tumor invasion, angiogenesis and metastasis." (PMID 32762747, 2020). "TIMP3 is an inhibitor of MMPs and its gene expression was significantly decreased in tumor tissues compared to controls (P = 0.0003)." (PMID 32171282, 2020). "We experimentally reasoned that circFNDC3B negatively and directly regulated miR‐937‐5p to induce the expression level of the tumor‐suppressor TIMP3, which inhibiting the metastasis, invasion and angiogenesis of CRC." (PMID 32896063, 2020). "In PCa, luciferase reporter assay demonstrated that both miR-17-5p/3p targeted the 3’-UTR of TIMP metallopeptidase inhibitor 3 (TIMP3), and ectopic expression of pre-miR-17 promoted tumor growth and invasion, which was mediated by TIMP3 repression." (PMID 33353171, 2020). "MicroRNA‐937‐5p downregulated TIMP3, thereby promoting tumor cell proliferation, invasion, migration and angiogenesis." (PMID 32896063, 2020). "TIMP-3 can bind to many proteinases to inhibit their activity and protect the ECM from degradation; nevertheless, reduced expression of TIMP-3 leads to poor outcomes, including large tumor size, high tumor stage, and metastasis." (PMID 33321708, 2020). "Q‐PCR analysis of tumor tissues revealed that relative expression levels of circFNDC3B and TIMP3 were upregulated in circFNDC3B overexpressing mice, whereas miR‐937‐5p was downregulated." (PMID 32896063, 2020). "Several studies have proved that TIMP3 functions as a tumor suppressor in many malignant tumors, including HCC." (PMID 32724322, 2020). "The tissue inhibitor of metalloproteinases (TIMP)-3 is a major regulator of extracellular matrix turnover via targeting of matrix metalloproteinases (MMPs), and thus, plays a critical role in tumor development and progression." (PMID 33126605, 2020). "In conclusion, our work reports a tumor‐suppressing role for the circFNDC3B–miR‐97‐5p–TIMP3 pathway and suggests that circFNDC3B‐enriched exosomes can inhibit angiogenesis and CRC progression." (PMID 32896063, 2020).